NOTCH3 (notch receptor 3)
Diseases named in the same sentence as NOTCH3 in open-access papers (continued):
Sharing a sentence is not in itself a finding about the gene and the disease.
cancer (continued). "About 90% (82 out of 93 cases, 88.2%) of the cases exhibited negative or occasional weak NOTCH3 expression in the cancer cells." (PMID 27124156, 2016). "Furthermore, results from Notch3 silencing and N3ICD overexpression demonstrated that NAC prevented malignant phenotypes through down-regulation of Notch3 protein in multiple cancer cells." (PMID 27102435, 2016). "Moreover, a strong correlation was evident between Notch3 and PCNA and between Cyclin G1 and PCNA supporting a role of both Notch3 and Cyclin G1 in cancer progression." (PMID 25431954, 2014). "An ion with 2223 m/z corresponding to the Notch3 peptide was detected in the majority of samples, such that the mean ion intensity in cancer patients was not significantly higher than in volunteers." (PMID 23226563, 2012). "In addition, JAG2, NOTCH1, and NOTCH3 tend to increase after anti-cancer therapy, although there is no significance." (PMID 39074091, 2024). "While CAFs-S1 stimulate cancer cell migration and initiate an EMT through CXCL12 and TGFB pathways, highly contractile CAFs-S4 induce cancer cell invasion in 3 dimensions via NOTCH signaling (NOTCH1, bSE = 3.0; NOTCH2, bSE = 2.6; NOTCH3, bSE = 1.4; NOTCH4, SE = 3.0)." (PMID 39335478, 2024). "In addition, overexpression of DRs such as PlexinD1, NOTCH3, c‐KIT, c‐MET, PTCH‐1, or TrkC has been reported in several cancer types, in contexts where their ligands are also expressed." (PMID 34542930, 2021). "Because Notch3-deficient mice exhibit modest vascular phenotypes but no serious defects and because NOTCH3 is not involved in NRF2-mediated cytoprotection, NOTCH3 inhibition is expected to exert anti-cancer effects without interfering with normal cellular functions in cancer-bearing hosts." (PMID 33219226, 2020). "Overall our findings indicate JMJD3 and p300 as general Notch1 and Notch3 signaling co-activators in T-ALL and suggest further investigation on the potential therapeutic anti-leukemic efficacy of their enzymatic inhibition in Notch/c-Myc axis-related cancers and diseases." (PMID 31001470, 2019). "We have demonstrated that regulation of the TCA cycle is a common mechanism in different human cancers, suggesting that Notch3 inhibitors combined with brivanib treatment may represent a strong formulation for the treatment of HCC as well as Notch3-driven cancers." (PMID 30765875, 2019). "Moreover, in obese patients, the cytokines produced by adipocytes and immune cells could promote the survival of cancer stem cells (CSCs) through the activation of the Notch3 and IL-6/JAK2/STAT3 pathways, as demonstrated in other cancer models." (PMID 30366466, 2018). "It would be of interest to study whether this function is conserved in other pathological situations where Notch3 is aberrantly expressed in non-endothelial cells, for example in cancer cells in which Notch3 and its ligands have been shown to be expressed." (PMID 28719575, 2017). "A previous study demonstrated that Notch3 protein degradation occurs in the endosome/lysosome compartments; therefore, we determined whether Notch3 cleavage fragments accumulated in OVCAR3 and MCF7 cancer cells in the presence of a lysosomal inhibitor." (PMID 25356737, 2014). "However, role of NOTCH3 has not been studied in gliomagenesis despite the fact that it plays central role in brain development and in cancer stem cell niche maintenance." (PMID 24143218, 2013).
cancer (continued). "However, the lack of correlation between Notch pathway compounds, clinical characteristics and outcome does not support their use as biomarkers.We observed that Notch3 is expressed in cancer cells, whereas Notch1 is mainly expressed in blood vessels." (PMID 22074495, 2011). "Additionally, only contact mediated coculturing of cancer cells could specifically induce NOTCH3, not observed when the cells were separated by a transwell, removing the probabilities of paracrine mechanisms." (PMID 38269089, 2023). "It was revealed that apelin could promote cancer cell proliferation by increasing expression of factors involved in cell proliferation including cyclin D1, Ki-67, proliferating cell nuclear antigen (PCNA), and activating pathways like JAG1/Notch3, ERK1/2, and PI3K/Akt." (PMID 33912466, 2021). "The ability of Notch3 to activate in the absence of DSL ligands suggests that it is likely that this constitutive activation mechanism plays a role in Notch3 signalling in cancer, particularly, given the high expression levels of Notch3 that are often observed." (PMID 32210034, 2020). "Further analysis of the correlation between NOTCH3 and SMARCA4 proteins in the CRC tissues and adjacent tissues revealed a significant positive correlation between them in the cancer tissues, but not in the adjacent tissues." (PMID 35900231, 2022). "Present data show that NILCO molecules (Notch1, Notch2, Notch3, Notch4, DLL4, and JAG1) and targets (Survivin, Hey2, IL-1R tI, and OB-R) were expressed in EmCa regardless of ethnicity and cancer type." (PMID 28659656, 2017). "We also examined the expression of other Notch receptors (Notch2, Notch3, and Notch4) in ICC tissue and noncancerous tissue adjacent to the cancer lesions." (PMID 23688168, 2013). "However, for the stemness marker correlation analysis, NOTCH3 did not exhibit co-expression with ALDH1A1 together with other stemness markers, suggesting NOTCH3 has little impact on keeping the cancer stemness in gastric tumorigenesis." (PMID 33452458, 2021). "Interestingly, two out of three TNBC samples not expressing EGFR are also Notch3 negative but express Notch1 (case 2), thus reinforcing the relevant Notch3-EGFR direct correlation in this cancer subtype." (PMID 29795369, 2018).
genetic disorder (15 papers, 2013 to 2025). "Since CADASIL is a genetic disorder linked to NOTCH3 missense mutations, this suggests the implication of glymphatic impairment in CADASIL progression." (PMID 39853935, 2025). "In conclusion, LMS is a serious genetic disorder associated with NOTCH3 pathogenic variants." (PMID 33519922, 2020). "The assay can be used to identify conditions that suppress NOTCH3 protein abnormalities and may be applied to other genetic disorders." (PMID 39864627, 2025).
neurodegenerative disease (9 papers, 2016 to 2024). A disorder of the central nervous system characterized by gradual and progressive loss of neural tissue and neurologic function. "More specifically, 1, 1, 312, and 4 mutations in Notch1, Notch2, Notch3, and Notch4, respectively, were identified to be correlated with neurodegenerative diseases." (PMID 38790158, 2024). "Since Notch3 is associated with the manifestation of neurodegenerative diseases to a considerably more significant degree than other human Notch family members, the annotation of Notch3 data followed." (PMID 38790158, 2024). "Since 90% of the mutations identified in Notch3 and related to neurodegenerative diseases were located in the EGF region, the mutation analysis was mainly focused on this specific region." (PMID 38790158, 2024). "Furthermore, Kyoto Encyclopedia of Genes and Genomes (KEGG) pathway analyses highlighted multiple neurodegenerative diseases as signatures associated with Notch3–/– aged mice." (PMID 38015629, 2024). "Other than the main effects of sleep deprivation on immune‐system function, plasma proteins associated with neurodegenerative diseases (APP, NOTCH3, SNCA, SOD1) were decreased after sleep deprivation, while only ATF6 continued to increase." (PMID 37139463, 2023). "Specifically, a set of haplotype-defining SNPs in NOTCH3 do not follow the Hardy–Weinberg equilibrium law in our complete cohort suggesting a role of NOTCH3 in the analysed neurodegenerative diseases." (PMID 35144616, 2022). "Other proteins such as prion protein (PRNP), neurogenic locus notch homolog protein 3 (NOTCH3), apolipoprotein E (APOE) associated with neurodegenerative diseases were also enriched in CSF exosomes." (PMID 26861304, 2016). "Additionally, single-cell RNA sequencing of the neuronal compartment in aging Notch3-null mice unveiled patterns reminiscent of those observed in neurodegenerative diseases." (PMID 38015629, 2024). "Lastly, PSEN2 Thr421Met may interact with other mutations in neurodegenerative disease related genes, which were found in the proband patient, such as ATP binding cassette subfamily A member 7 (ABCA7), Notch Receptor 3 (NOTCH3), or Leucine-rich repeat kinase 2 (LRRK2)." (PMID 36362122, 2022).
vasculopathy (9 papers, 2013 to 2024). "The syndrome is mainly caused by cysteine-altering pathologic variants in the NOTCH3 gene, leading to vasculopathy changes involving the small penetrating arteries, arterioles, and brain capillaries." (PMID 36465750, 2022). "In addition, other mechanisms leading to vasculopathy different from accumulation of Notch3 intracellular domain cannot be ruled out." (PMID 34335700, 2021).
infection (7 papers, 2010 to 2022). The state of being infected such as from the introduction of a foreign agent such as serum, vaccine, antigenic substance or organism. "We overexpressed the intracellular domains of the Notch2 (NICD2) and Notch3 (NICD3) by lentiviral infection of human aortic smooth muscle cells and examined gene expression by qPCR." (PMID 22615991, 2012). "When Notch3 expression was induced after Ad-Cre infection, we found that Jagged1 transcript and protein level were elevated as compared to the same cells infected with Ade-GFP control virus." (PMID 20953350, 2010). "Accordingly, the increased expression of DLL4 and NOTCH3 may provide the stimulus to activate crypt cell proliferation to replace the enterocytes lost to apoptosis early in infection." (PMID 23593167, 2013). "We have shown that when Notch3 is transfected in renal tubular cells induces the expression of MCP‐1, RANTES and cell proliferation, and that infection of podocytes with Notch3‐carrying viruses induces NF‐κB expression." (PMID 35611804, 2022). "We validated in two cell-lines (Caco-2 and HT-29) the changes in expression of a number of genes (MT1E, NPPB, NOTCH3, CYP26A1, HEY1 and CYP1A1) found to be differentially expressed using RNAseq following infection with C. concisus UNSWCD or BAA-1457." (PMID 27677841, 2016). "However, 8 days after AdHGF infection of VSMCs, Notch3 was mainly localised in the nuclei, suggesting HGF over-expression triggers Notch3 activation." (PMID 21920521, 2011).
adenocarcinoma (5 papers, 2013 to 2023). A common cancer characterized by the presence of malignant glandular cells. "The highest Notch3 expression was observed in the adenocarcinoma group compared with the other two groups and the difference was statistically significant (P<0.01)." (PMID 23420695, 2013). "We thus treated cells of the human adenocarcinoma cell line, MDA-MB-231, that express very low amounts of Notch3, with 5-azacitidine (5-aza) a well-known DNA demethylation agent." (PMID 36854682, 2023).
cardiovascular disease (5 papers, 2019 to 2024). "NOTCH3-specific drugs combined with targeted drug delivery may revolutionize the treatment of cardiovascular disease with minimal side effects, and warrant further investigation." (PMID 35229725, 2022). "NOTCH3-specific therapies or therapies that target downstream molecular pathways may provide opportunities to minimize VSMC growth and treat cardiovascular disease with minimal side effects." (PMID 35229725, 2022).
kidney (5 papers, 2016 to 2024). "Notch receptor 3 (NOTCH3) was more frequently mutated in the high CD8 T cell group; in NOTCH3 deficient mice following tubular kidney injury, monocytic cell infiltration was shown to be reduced, likely due to abrogated chemokine synthesis." (PMID 33633150, 2021). "The Notch3 upregulation facilitates the autologous invasion and migration of lung adenocarcinoma cells." (PMID 38169645, 2024). "The METTL3-mediated m6A modification level of TIMP2 mRNA may promote podocyte injury, apoptosis in glomeruli, and kidney inflammation through upregulating the Notch3 and Notch 4 signaling pathways." (PMID 36157472, 2022).
kidney disease (5 papers, 2020 to 2025). "The abnormal activation of Notch3 plays a key role in kidney disease and directly affects the prognosis of kidney disease." (PMID 35630598, 2022). "We have previously demonstrated that in chronic and acute kidney injury models, Notch3 is de novo expressed by suffering cells to promote renal inflammation and fibrosis and aggravate the progression of renal disease." (PMID 35611804, 2022). "Here, we discuss numerous recently published papers describing the role of Notch3 signaling in kidney disease." (PMID 33149805, 2020). "We have found recently that activation of Notch3, a mediator of vascular smooth muscle cell proliferation and dedifferentiation, promotes renal inflammation and fibrosis and aggravates progression of renal disease." (PMID 35611804, 2022). "Thus, our previous results establish de novo activation of Notch3 as a novel pro‐inflammatory mediator which controls the phenotype of injured cell populations and promotes the progression of renal disease." (PMID 35611804, 2022). "The abnormal activation of Notch3 promotes the proliferation of a variety of cells, such as intrinsic glomerular cells, tubular epithelial cells, and interstitial fibroblasts, which mediate the occurrence and development of renal diseases." (PMID 33149805, 2020). "However, the identity of the cell types in which Notch3 is activated in different renal diseases is an unsolved issue that might shed light on the effects of Notch3 signaling." (PMID 33149805, 2020). "Thus, an enhanced understanding of Notch3 may be beneficial for the development of therapeutic options to delay the progression of kidney disease." (PMID 33149805, 2020). "However, recent studies have shown that Notch3 is abnormally activated, plays important roles in a variety of glomerular and tubulointerstitial diseases, and directly affects the prognosis and outcome of nephropathy." (PMID 33149805, 2020). "This review summarizes the recent advances in the understanding of Notch3 in nonneoplastic kidney diseases." (PMID 33149805, 2020). "The role of Notch3 in inflammation has been studied in non-HIV kidney diseases." (PMID 39910908, 2025). "Mice lacking Notch3 were significantly protected against the progression of renal disease in these models, whereas mice genetically modified to express a continuously activated Notch signalling were progressing faster towards loss of renal function and structure." (PMID 35611804, 2022).
neurological diseases (5 papers, 2019 to 2025). "Particularly, two additional rare variants were found in the proband patient, which were risk genes, NOTCH3 and GBA, for other neurological diseases." (PMID 39273625, 2024).
gastrointestinal tumors (2 papers, 2022 to 2024). "NOTCH3 was found to be commonly overexpressed in various types of gastrointestinal tumors and was significantly associated with poor prognosis." (PMID 38906903, 2024). "We further found NOTCH3 levels in gastrointestinal tumor to correlate with markers of Dendritic cell(HLA-DPB1, HLA-DRA, HLA-DPA1, BDCA-4), Tfh(T-bet, STAT4, STAT1, TNF-α), Treg cells (FOXP3, CCR8, STAT5B, TGFβ) and T cell exhaustion (PD-1, CTLA4, LAG3, TIM-3)." (PMID 38906903, 2024). "Taken together, these results highlight the ability of NOTCH3 to potentially regulate immune cell recruitment and activation in gastrointestinal tumor." (PMID 38906903, 2024). "It’s interesting to note that NOTCH3 was also discovered to significantly affect patient prognoses for a few other non-gastrointestinal tumours." (PMID 38906903, 2024). "In summary, NOTCH3 may be an important regulator of immune cell infiltration in patients with gastrointestinal tumors, a valuable prognostic biomarker and even a potential therapeutic target." (PMID 38906903, 2024).
autosomal recessive disease (1 paper, 2023). Autosomal recessive form of disease. "With our study, we provided Moderate or Strong level of evidence for GDR for 11 genes that were not listed in OMIM as having phenotype entity: FBRSL1, AGR2, ACBD6, C1orf127, PAN2, VPS50, KCTD3, NOTCH3 (for autosomal recessive disease), FAT1, NRAP, and SCLT1." (PMID 39669245, 2023).
immune disorders (1 paper, 2021). "However, recent work reported new functional roles for Notch3 and Notch4 in other cells relevant to immune disorders such as synovial fibroblasts and macrophages for Notch3, and regulatory T cells for Notch4." (PMID 34124039, 2021).
inflammation (1 paper, 2022). Aberrant reaction of the microcirculation characterized by movement of fluid and leukocytes from the blood into extravascular tissues. "Synovial inflammation also results in the activation of THY-expressing sublining fibroblasts that depend on endothelial-derived Notch3 and further promote synovial inflammation." (PMID 35547214, 2022).
respiratory diseases (1 paper, 2025). "Notch signaling pathway, particularly Notch3/4, plays a key role in ozone-induced disruption of lung circadian rhythms, which establishes a novel mechanistic link between environmental pollutants and circadian rhythm gene alterations in respiratory diseases." (PMID 41012354, 2025).
NOTCH3 also shares sentences with these, for which no sentence is quoted: migraine with aura (9 papers); infarcts (6); endometriosis (5); myofibromatosis (5); Fabry disease (4); Parkinsonism (3); Ataxia (2); autosomal dominant disease (2); bladder urothelial carcinoma (2); cardiac disease (2); chronic myeloid leukaemia (2); cognitive disorder (2); diffuse large B-cell lymphoma (2); ductal carcinoma in situ (2); Ehlers-Danlos syndrome (2); gastric tumors (2); glomerulonephritis (2); head and neck cancer (2); homocystinuria (2); insomnia (2); lipodystrophies (2); mantle cell lymphoma (2); MELAS (2); metabolic disease (2); metastatic carcinoma (2); mood disorder (2); polycystic kidney disease (2); transient ischaemic attack (2); alcoholic liver cirrhosis (1); Alstrom syndrome (1).
A further 125 diseases each share a sentence with NOTCH3 in 1 paper.